RB1 (RB transcriptional corepressor 1)
Diseases named in the same sentence as RB1 in open-access papers (continued):
Sharing a sentence is not in itself a finding about the gene and the disease.
breast cancer (continued). "miR-335 appears to control growth by blocking cell proliferation by targeting certain genes; e.g., RASA1 in rat epididymal development, SP1 and Bcl-w in non-small cell lung cancer, SOX4 and TNC in breast cancer, ROCK1, MAPK1, and LRG1 in neuroblastoma, and Rb1 in U2OS osteosarcoma cells." (PMID 26204513, 2015). "RB1CC1 is a novel regulator of RB1 that dephosphorylates RB1 and increases its expression; in addition, a genetic rearrangement of RB1CC1 might be involved in breast cancer tumorigenesis." (PMID 20614030, 2010). "Lack of pRb protein and loss of heterozygosity (LOH) at the RB1 locus have been related to triple negative (TNBC) or basal cell-like breast cancer." (PMID 20594292, 2010). "RB1 mRNA level was down-regulated in MCF-7 breast carcinoma cells by the overexpression of ZNF191 (data not published)." (PMID 19463170, 2009). "We conclude that, if the observed associations are real, it is likely that it is variation related to RB1 and not P2RY5 that modifies breast cancer susceptibility." (PMID 16685266, 2006). "Furthermore, transcriptomic analyses and Western blot assays have confirmed pronounced OXPHOS upregulation in breast cancers lacking RB1 expression." (PMID 41465397, 2025). "Specifically, lack of functional RB1, may lead to increased resistance to hormone therapy, e.g. tamoxifen treatment in breast cancers, kinase inhibitor treatment and immunotherapy." (PMID 37917619, 2023). "Also, no mutations were detected for other described breast cancer‐associated genes (e.g., RAD51, RAD50, p27, ESR1/2, ERBB2, ERBB3, AKT1, CCDN1, FGFR1, MYC, and RB1) in any of the tissues or the CTC cell line." (PMID 32667137, 2020). "However, in a human breast cancer cell line MCF-7, Rb1 seems to bind both ER-α and ER-β receptors." (PMID 30642080, 2019). "In breast cancer, 17 genes, including RNF8, DYRK2, RB1, and TRDMT1, could be used as prognostic biomarkers of breast cancer, indicating that these genes, including RNF8, might have a strong relationship with breast cancer." (PMID 31709182, 2019). "Moreover, the expression of AR is correlated with RB1 in patients with TNBC and breast cancer." (PMID 29261702, 2017). "This group of patients (Rb1+, ER+) could be a target for CDK4/6 inhibition plus letrozole, with or without antiestrogen therapy, a regimen with proven efficacy in patients with advanced ER+ breast cancer." (PMID 26043844, 2015). "Lack of RB1 in many tumors has been widely proven, and breast cancer is not an exception." (PMID 24403251, 2013).
breast cancer (continued). "Moreover, knocking-down of βTrCP1 suppressed HFF1 cell proliferation, in which RB1 proteins were mainly in hypophosphorylated form and supposed to have higher affinity with βTrCP1, and enhanced the inhibitory effect of CDK4/6i on MCF7 breast cancer cell proliferation." (PMID 34508104, 2021). "In addition, when a panel of 47 human breast cancer and immortalized breast cell lines grown in vitro were treated with a CDK4/6 inhibitor (palbociclib), sensitive cell lines (estrogen receptor positive) showed increased expression of the genes RB1 and CCND1 and reduced expression of CDKN2A (p16)." (PMID 30443290, 2018). "Since pRB-dependent negative growth control is dramatically reduced in the mammary glands of Rb1ΔL mice, but viability and overall development are normal, these animals provide a unique opportunity to examine the impact of negative growth signals in suppressing mammary cancer." (PMID 21364977, 2011). "In breast cancer alone, up to 50% of patients with Rbness in the absence of RB1 genomic alterations harbored amplifications in PIK3CA, RB (CCND1 and CCNE1), and ER signaling modules (ESR1, FOXA1, and GATA3)." (PMID 40138429, 2025). "In addition, METTL1 inhibited breast cancer (BC) cell cycle progression and proliferation by promoting the translation of growth arrest and DNA damage 45 alpha (GADD45A) and retinoblastoma protein 1 (RB1) mRNAs, selectively blocking the G2/M phase of the cell cycle." (PMID 39979979, 2025). "Inactivation of Tsc2 specifically killed Rbf1-deficient cells in the Drosophila eye; induced cell death in RB1-mutant DU145 prostate cancer cells, Saos-2 osteosarcoma cells, and MDA-MB-468 breast cancer cells but not in their RB1-wild type counterparts; and inhibited tumor growth in nude mice." (PMID 33591981, 2021).
prostate carcinoma (222 papers, 1994 to 2026). A carcinoma that arises from epithelial cells of the prostate gland. "The retinoblastoma tumor suppressor gene RB1 is frequently inactivated in prostate cancer, primarily through deletion mutations and aberrant phosphorylation." (PMID 41492471, 2026). "The RB1/E2F1 axis is closely associated with prostate cancer neuroendocrine differentiation, and its dysregulation is linked to uncontrolled cell cycle progression during cancer development." (PMID 41492471, 2026). "Here, using a range of patient-derived prostate cancer models, the authors demonstrate that increased replication stress induced by RB1 loss confers sensitivity to BH3 mimetics targeting BCL-XL." (PMID 40436896, 2025). "Consistent with these DNA damage response results, single sample gene set enrichment analysis (GSEA) of TCGA primary prostate cancers showed that those with RB1 loss had an increase in the gene set ATR Activation in Response to Replication Stress." (PMID 40436896, 2025). "Studies evaluating CDK4/6 inhibitors in prostate cancer should assess if selective pressure leads to increased RB1 loss and increased small-cell transformation in prostate cancer patients, as this would constitute a significant treatment-related adverse event." (PMID 40075623, 2025). "Rb1 undergoes mutations in several types of cancers, including retina, lung, prostate cancer, osteosarcoma, glioma, among others." (PMID 39845333, 2025). "In this work we screen a diverse panel of prostate cancer patient-derived models for responses to navitoclax, and find that RB1 loss is associated with increased sensitivity." (PMID 40436896, 2025). "Through assessment of xenograft-derived 3D prostate cancer models and cell lines we find that tumors with RB1 loss are sensitive to BCL-XL inhibition." (PMID 40436896, 2025). "Lastly, RB1 is a tumor suppressor gene that controls cell cycle progression; mutations in RB1 lead to uncontrolled cell division and are found in various cancers, including bladder and prostate cancer." (PMID 39590142, 2024). "There is growing consensus suggesting that RB1 mutations play a critical role in the development of various cancers, including breast and prostate cancer." (PMID 39664374, 2024). "The current study reports on RNASEH2B protein loss in advanced prostate cancer and its association with RB1 protein loss, clinical outcome, and clonal dynamics during treatment with PARP inhibition in a prospective clinical trial." (PMID 38833311, 2024). "Although both gene's mutations are present in both NEPC and castration‐resistant prostate cancer, RB1 mutations can be found in much higher frequencies in NEPC than in the castration‐resistant form of the disease." (PMID 39410867, 2024).
prostate carcinoma (continued). "This study underscores the importance of further exploring the therapeutic potential of LSD1 inhibitors in treating aggressive forms of prostate cancer characterized by RB1 loss." (PMID 38672640, 2024). "This case report outlines a patient with a retinoblastoma tumor suppressor gene (RB1) mutation and prostate cancer metastasis to the bone incidentally noted to have an enhancing, extra-axial mass on a screening MRI." (PMID 37900533, 2023). "We found that JKE-1674 treatment significantly extended median overall survival of PPR-RFP mice from 42 to 49 weeks, further corroborating the potent antitumor and antimetastatic activity exhibited by ferroptosis against RB1-deficient prostate cancer." (PMID 36928314, 2023). "Further studies are needed to determine the potential role of the E2F3 cistrome in mediating RB1 loss–driving prostate cancer progression and therapeutic vulnerabilities." (PMID 36928314, 2023). "RHAMM has also been reported to be induced following RB1 loss, is an E2F target gene and affords a metastatic potential for prostate cancer cells through the Rho-associated kinase signaling pathway." (PMID 37546702, 2023). "Significant prevalence differences compared to TCGA were identified, including a high prevalence of EGFR in lung (P = 0.001); RB1 in breast (P = 0.0002); and multiple mutations in prostate cancer." (PMID 37702806, 2023). "RB1 loss of function is infrequent in primary untreated prostate cancer and is associated with poor prognosis in patients with metastatic CRPC, in part due to its key role in lineage plasticity and NEPC progression." (PMID 37704749, 2023). "Our data establish the RB/E2F/ACSL4 axis as a rheostat of ferroptosis that can be exploited for the treatment of RB1 loss–driven prostate cancer." (PMID 36928314, 2023). "Both pre-mRNA splicing inhibitors induced a dose-dependent response and had higher selectivity in RB1-deficient prostate cancer cells." (PMID 33591981, 2021). "While RB1 loss is common in prostate cancer and N-Myc overexpression occurs in a large proportion of NEPC, little is known about the potential synergy between these two events." (PMID 34099734, 2021). "RB1 loss promotes lineage transformation in prostate cancer via the upregulation of epigenetic and reprogramming factors including EZH2." (PMID 32292420, 2020). "In one study, it was shown that RB1 loss facilitates lineage plasticity and metastasis of prostate cancer initiated by PTEN mutation." (PMID 31366128, 2019).
prostate carcinoma (continued). "Taken together, these findings suggest that deregulation of the MYC/E2F1/RB1 cell-cycle regulator axis by various means is a ubiquitous event in AR indifferent prostate cancer that is necessary to overcome the G1 arrest caused by low AR activity." (PMID 31551480, 2019). "The retinoblastoma tumor suppressor gene RB1 is more commonly loss in metastatic and antiandrogen resistant prostate cancer (74% of cases) and NEPC (90% of cases) than it is in primary tumors (34% of cases)." (PMID 29888169, 2018). "The RB1 gene is altered in nearly 9% of advanced prostate cancer cases, through deletion, frameshift mutations, and introductions of premature stop codons." (PMID 28228136, 2017). "NUSAP1 expression is regulated by E2F transcription factor 1 (E2F1) and by loss of retinoblastoma-associated protein 1 (RB1), an important molecular pathway that becomes altered in aggressive forms of prostate cancer." (PMID 28404898, 2017). "We previously found that NUSAP1 is overexpressed in recurrent prostate cancer and is regulated, at least in part, by loss of RB1 via the RB1/E2F1 axis." (PMID 28404898, 2017). "Loss of RB1 is common in prostate cancer, controls progression into castration-resistant prostate cancer, and is a mechanism responsible for overexpression of NUSAP1." (PMID 28404898, 2017). "Despite the conservative approach and the overall limited number of samples, we observed that RB1 loss is consistently sequential to 6q losses in both melanomas and prostate cancers." (PMID 25160065, 2014). "Notably, in three independent cohorts of advanced prostate cancer, RB1 deletion mutations significantly up-regulated the expression of CDRs." (PMID 41492471, 2026). "Interestingly, RB1 loss has been identified as an alteration occurring early in prostate cancer development that drives clinical aggression through subclonal diversification." (PMID 40840524, 2025). "Moreover, RB1 loss in prostate cancer is associated with increased expression of genes involved in DNA damage repair." (PMID 40436896, 2025). "Importantly, RB1 loss is also present in 70–90% of small-cell neuroendocrine carcinomas of the prostate, a particularly aggressive form of prostate cancer." (PMID 40075623, 2025). "Additionally, RB1 loss in primary prostate cancer has been associated with poorer survival outcomes, and another study reported its correlation with the development into a castration‐resistant state and worse clinical outcomes." (PMID 38379333, 2024). "Similar to ENOC, in prostate cancer, RB1 loss is associated with poorer survival: early somatic co-deletion of BRCA2 and RB1 is associated with an aggressive, castration-resistant prostate cancer subtype characterized by epithelial-to-mesenchymal transition and shorter survival." (PMID 38837893, 2024).